HOTAIR (HOX transcript antisense RNA)
Diseases named in the same sentence as HOTAIR in open-access papers (continued):
Sharing a sentence is not in itself a finding about the gene and the disease.
cholangiocarcinoma (1 paper, 2021). A carcinoma that arises from the intrahepatic biliary tree (intrahepatic cholangiocarcinoma) or from the junction, or adjacent to the junction, of the right and left hepatic ducts (hilar cholangiocarcinoma). "In a Greek cohort of patients, HOTAIR rs4759314 AG and GG genotypes were associated with a significantly increased cholangiocarcinoma risk." (PMID 34576322, 2021). "The analysis of polymorphisms in the gene sequence of HOTAIR to evaluate the susceptibility to the development of cholangiocarcinoma has recently been evaluated." (PMID 34576322, 2021). "HOTAIR silencing significantly decreased the migration and invasion and increased apoptosis of cholangiocarcinoma cell models." (PMID 34576322, 2021). "HOTAIR was highly expressed both in cholangiocarcinoma tissues and cell lines compared with corresponding normal bile duct tissues and intrahepatic biliary epithelial cells." (PMID 34576322, 2021).
cognitive decline (1 paper, 2024). "Further, elevated serum expression of HOTAIR in AD patients has been reported to elicit close associations with the severity of cognitive and memory impairments, encouraging the proposition of serum HOTAIR levels as a biomarker for cognitive decline in AD." (PMID 38366205, 2024).
Cognitive impairment (1 paper, 2025). Abnormal cognition is characterized by deficits in thinking, reasoning, or remembering. "Furthermore, lower Mini-Mental State Examination (MMSE) scores and higher ADAS-Cog scores, which are commonly used markers of cognitive impairment in AD, demonstrated that higher levels of HOTAIR expression were associated with worse cognitive performance." (PMID 39920595, 2025). "This suggests that HOTAIR could play a role in the cognitive deficits associated with AD and may be a target for treatment approaches." (PMID 39920595, 2025). "By reducing HOTAIR expression, exercise may help mitigate the detrimental effects of HOTAIR on cognitive impairment." (PMID 39920595, 2025).
colorectal tumors (1 paper, 2021). "We further compared the expression levels of HOTAIR, MALAT1 and LOC285194 in primary colorectal tumors at the time of initial diagnosis and correlated them with disease progression and liver metastasis." (PMID 34307387, 2021).
craniosynostosis (1 paper, 2022). Craniosynostosis is defined as the premature fusion of one or more cranial sutures leading to secondary distortion of skull shape resulting in skull deformities with a variable presentation. "In this study, our data showed that HOTAIR expression was significantly downregulated in PBMCs from children with craniosynostosis." (PMID 35360844, 2022). "In this study, we aimed to investigate the molecular role of HOTAIR in the osteoclast function and development of craniosynostosis.For osteoclast differentiation, RAW264.7 cells were induced by 50 ng/ml of RANKL and 10 ng/mL M-CSF, followed by TRAP staining." (PMID 35360844, 2022). "In this study, our findings demonstrated the role of HOTAIR in craniosynostosis through modulating miR-152 and its target gene CAMKIIα." (PMID 35360844, 2022). "qRT-PCR results showed that HOTAIR expression was significantly lower in the craniosynostosis children’s group than the control group (p < 0.05)." (PMID 35360844, 2022). "The HOTAIR expression in PBMCs from children with craniosynostosis was significantly downregulated." (PMID 35360844, 2022). "All those results implied that HOTAIR might regulate osteoclast formation to participate in the development of craniosynostosis." (PMID 35360844, 2022). "Therefore, the results observed in our animal model and the possible role of HOTAIR in craniosynostosis seem to be related to the fact that HOTAIR favors bone resorption while inhibiting bone formation." (PMID 35360844, 2022). "Moreover, the luciferase reporter assay results showed that the regulatory axis, HOTAIR-miR-152-CAMKIIα, was the regulatory mechanism of HOTAIR in the osteoclast function and development of craniosynostosis." (PMID 35360844, 2022). "This study aimed to investigate whether HOTAIR plays a regulatory role in osteoclast differentiation in craniosynostosis development through the miR-152/CAMKII α axis." (PMID 35360844, 2022). "However, whether HOTAIR plays an essential role in the development of craniosynostosis is still unclear." (PMID 35360844, 2022).
depression (1 paper, 2024). "The lncRNAs HOTAIR and MALAT1 are dysregulated in depression and have been implicated in the modulation of gene expression and cellular processes relevant to depression." (PMID 39194576, 2024). "For instance, HOTAIR is an lncRNA that has been shown to play a role in chromatin remodeling and gene silencing during depression and can influence genes related to mood regulation and stress responses in a very similar vein." (PMID 39194576, 2024). "HOTAIR binds to the polycomb repressive complex 2, as has been reported in depression research." (PMID 39194576, 2024). "Furthermore, research has demonstrated that HOTAIR functions as a potent oncogene in various depressive disorders by modulating chromatin dynamics." (PMID 39194576, 2024).
ductal carcinomas (1 paper, 2015). "Further analysis of TCGA dataset showed that HOTAIR expression was lower in ductal carcinomas but higher in ER-negative tumors." (PMID 25739705, 2015).
ependymoma (1 paper, 2021). A WHO grade II, slow growing tumor of children and young adults, usually located intraventricularly. "Nevertheless, a more recent study analyzed HOTAIR expression in adult myxopapillary ependymoma (MPE), highlighting its overexpression compared with non-ependymoma spinal tumors." (PMID 34576322, 2021).
Ewing sarcoma (1 paper, 2020). A small round cell tumor that lacks morphologic, immunohistochemical, and electron microscopic evidence of neuroectodermal differentiation. "MET gene expression was significantly upregulated by HOTAIR repression in ES2 and SK-ES Ewing Sarcoma cell lines and its expression was significantly repressed by HOTAIR over-expression in hTERT-immortalized human mesenchymal stem cells." (PMID 32650779, 2020). "In GSE109483 dataset, researchers repressed HOTAIR expression in three Ewing sarcoma cell lines (ES2, A673, SK-ES) and overexpressed HOTAIR in hTERT-immortalized human mesenchymal stem cells to evaluate its effects on gene expression." (PMID 32650779, 2020).
gastritis (1 paper, 2019). Inflammation of the stomach. "The expression levels of HOTAIR in 54 GC tissues and their matched adjacent nontumor tissues from GC patients and 24 normal mucosa or those with minimal gastritis as healthy controls were determined by qRT-PCR." (PMID 31281803, 2019).
hyperuricaemia (1 paper, 2021). "In this study, we found that the expression level of HOTAIR in hyperuricaemia patients was significantly higher than that in the normal population." (PMID 34296520, 2021). "In HUA‐treated HUVECs and hyperuricaemia mice, we observed increased HOTAIR and decreased miR‐22 expression." (PMID 34296520, 2021). "Compared with that in serum from healthy individuals, the expression of HOTAIR in serum from hyperuricaemia patients was significantly higher." (PMID 34296520, 2021). "Furthermore, in vivo experiments validated that HOTAIR knockdown alleviated renal inflammation in hyperuricaemia mice." (PMID 34296520, 2021). "We observed a decrease in serum miR‐22 expression in hyperuricaemia patients and a negative correlation between miR‐22 and HOTAIR expression." (PMID 34296520, 2021).
idiopathic scoliosis (1 paper, 2019). A scoliosis with no known cause. "The results showed that the expression of HOTAIR was significantly upregulated in IDD patients compared to that in idiopathic scoliosis patients." (PMID 31481088, 2019). "To study the role of HOTAIR in the pathogenesis of IDD, we measured the expression of HOTAIR in NP tissues from idiopathic scoliosis patients or IDD patients using qRT-PCR." (PMID 31481088, 2019).
IgA nephropathy (1 paper, 2024). "Notably, the research posited that HOTAIR emerged as the principal lncRNA regulating differentially expressed genes and microRNAs in the context of IgA nephropathy." (PMID 38958113, 2024).
Insulin resistance (1 paper, 2022). Increased resistance towards insulin, that is, diminished effectiveness of insulin in reducing blood glucose levels. "So far, a limited number of studies have been conducted on the association between HOTAIR and insulin resistance in T2DM patients." (PMID 35359879, 2022).
keloid (1 paper, 2022). An irregularly shaped, elevated mark on the skin caused by deposits of excessive amounts of collagen during wound healing. "PCR showed that LEP, CIDEC and lncRNA HOTAIR showed increased expression (p < 0.05) in trunk keloid of trunk, while none showed statistical difference in ear keloid." (PMID 35677827, 2022).
leukopenia (1 paper, 2023). "In conclusion, the present study found that HOTAIR rs7958904 gene polymorphism can be serve as a suggested biomarker to find patients with Leukopenia." (PMID 38087305, 2023). "However, the frequencies of rs7958904 CC genotype and C allele in the HOTAIR gene were significantly correlated with leukopenia in PTB patients." (PMID 38087305, 2023). "Notably, the HOTAIR rs7958904 CC genotype and C allele exhibited a significant increase in PTB patients with leukopenia compared to those without leukopenia." (PMID 38087305, 2023). "Subsequently, we observed that the mRNA level of HOTAIR and THRIL genes exhibited no discernible correlation with the occurrence of clinical features, including fever, drug resistance, liver injury, lung infection, hypoproteinemia, leukopenia, and positive sputum smear in PTB patients." (PMID 38087305, 2023).
mesenchymal tumor (1 paper, 2016). "As GISTs are the most common mesenchymal tumor, we looked at the effect of HOTAIR silencing on the levels of epithelial-mesenchymal transition (EMT)-related markers in cell lines originating from GISTs." (PMID 27659532, 2016).
mesothelial neoplasm (1 paper, 2019). A benign or malignant neoplasm arising from mesothelial cells. "It was found that there is, also, a strong relationship between HOTAIR overexpression and poor OS in neoplasms of the adrenal cortex, mesothelial neoplasms, and neuroepithelial tumors." (PMID 31195674, 2019).
Miscarriage (1 paper, 2022). A pregnancy that ends at a stage in which the fetus is incapable of surviving on its own, defined as the spontaneous loss of a fetus before the 22th week of pregnancy. "HOTAIR was a regulatory factor regulating the proliferation, migration and invasion of trophoblasts, and the abnormality of HOTAIR leads to miscarriage." (PMID 35501804, 2022).
muscle atrophy (1 paper, 2025). The loss of muscle tissue due to inactivity or disease. "In addition, H19, HOTAIR, MALAT1 and PVT1 are highly expressed in the kidneys of CKD patients and are associated with muscle atrophy but do not directly mediate the pathogenesis of muscle atrophy in CKD patients." (PMID 40034097, 2025).
myeloid leukemia (1 paper, 2022). A clonal proliferation of myeloid cells and their precursors in the bone marrow, peripheral blood, and spleen. "The ability of YTHDC1 to form phase separated nuclear condensates, which has been shown to stabilize m6A-modified RNAs in myeloid leukemia cells, may play a role in stabilizing HOTAIR, providing a large reservoir that leads to aberrant targeting of genomic loci in cancer." (PMID 36441764, 2022).
nephritis (1 paper, 2022). Inflammation of renal tissue. "Furthermore, HOTAIR expression level had significantly positive correlation with IL-6 (r = 0.578, P<0.0001), MMP-9 level (r = 0.762, P<0.0001), nephritis grades (r = 0.296, P = 0.024) and proteinuria (r = 0.287, P = 0.035)." (PMID 35972968, 2022).
neuroendocrine tumors (1 paper, 2021). "Numerous lncRNAs have been associated with neuroendocrine tumors pathogenesis especially in gastroenteropancreatic neuroendocrine tumors (GEP-NET); however, the role of HOTAIR is still poorly investigated." (PMID 34576322, 2021).
non-Hodgkin lymphoma (1 paper, 2021). Distinct from Hodgkin lymphoma both morphologically and biologically, non-Hodgkin lymphoma (NHL) is characterized by the absence of Reed-Sternberg cells, can occur at any age, and usually presents as a localized or generalized lymphadenopathy associated with fever and weight loss. "Conclusively, our findings showed that rs1899663 of HOTAIR significantly decreased the risk of non-Hodgkin Lymphoma." (PMID 34582651, 2021).
osteonecrosis (1 paper, 2024). A none disease characterized by death of bone tissue due to a lack of blood supply. "In addition to its role in development, HOTAIR has been implicated in the pathogenesis of osteonecrosis, a condition characterized by the death of bone tissue due to a lack of blood supply." (PMID 39156986, 2024). "The researchers observed that HOTAIR expression was upregulated in osteonecrosis tissues compared to normal tissues." (PMID 39156986, 2024). "However, recent studies have also revealed HOTAIR’s involvement in other diseases, such as osteonecrosis and developmental disorders." (PMID 39156986, 2024).
panic disorder (1 paper, 2023). An anxiety disorder characterized by multiple unexpected panic attacks with persistent concern of recurring attacks. "Regarding panic disorder, data from our study indicates that the levels of DISC2, PANDA, HOTAIR, MALAT1 and GAS5 lncRNAs are over-expressed in the T1 patient group, while the T2 patients show similar levels to the controls." (PMID 37761918, 2023). "Further novelty concerns the gene expression levels of ncRNAs in Panic Disorder patients: from our observations, it was found that the ncRNAs DISC2, GAS5, HOTAIR, MALAT1, PANDA and miR-221-5p are significantly over-expressed in the T1 patients group compared with healthy controls." (PMID 37761918, 2023).
Patent ductus arteriosus (1 paper, 2020). In utero, the ductus arteriosus (DA) serves to divert ventricular output away from the lungs and toward the placenta by connecting the main pulmonary artery to the descending aorta. "Regarding lncRNAs in CHDs, HOTAIR was found to be upregulated in both myocardial tissue and plasma samples of ASD, VSD, and patent ductus arteriosus (PDA) patients when compared with healthy subjects, and thus was indicated as a potential biomarker for CHD." (PMID 33291434, 2020).
Pca (1 paper, 2021). "HOTAIR is overexpressed in both PCa tissues and in cell lines." (PMID 34367966, 2021). "HOTAIR was upregulated in PCa cells and promoted tumorigenesis through epigenetic regulation." (PMID 34367966, 2021).
premature ovarian failure (1 paper, 2023). "The expression of HOTAIR in ovarian tissue and serum of patients with premature ovarian failure can accurately predict the risk of premature ovarian failure." (PMID 36845376, 2023). "At the same time, HOTAIR may also interact with the Notch pathway which plays an important role in premature ovarian failure." (PMID 36845376, 2023).
prostate tumors (1 paper, 2020). "Interestingly, among the common up-regulated targets, UGT2B15 and HOTAIR were described to be inhibited by AR in prostate tumors and activated by ESR1." (PMID 32041153, 2020).
rosacea (1 paper, 2020). A chronic erythematous skin disorder that affects the face. "Upregulated NEAT1 can be a possible biomarker for rosacea diagnosis as well as HOTAIR and ZNF667-AS1 can be a target for rosacea prevention and treatment." (PMID 32185228, 2020). "In our study, the downregulated expression of HOTAIR in all subtypes of rosacea indicates that HOTAIR may improve rosacea by alleviating inflammation and inhibiting the NF-kappa B pathway." (PMID 32185228, 2020). "The results by RT-qPCR revealed the increased expression of NEAT1 and decreased expression of HOTAIR, ZNF667-AS1 in rosacea tissues, which was consistent with microarray." (PMID 32185228, 2020). "FISH staining (Merge) confirmed the increased expression of NEAT1 and decreased expression of HOTAIR and ZNF667-AS1 in rosacea compared to normal adjacent specimens." (PMID 32185228, 2020). "In addition, we found nine differentially expressed lncRNAs in all three rosacea subtype-related networks, including NEAT1 and HOTAIR, which may play important roles in the pathology of rosacea." (PMID 32185228, 2020).
skin cancer (1 paper, 2024). "In addition, HOTAIR expression level was decreased in skin cancer (P < 0.05)." (PMID 38696320, 2024).
thoracic aortic aneurysm (1 paper, 2022). An aneurysm formed in the wall of the proximal portion of the descending aorta proceeding from the arch of the aorta. "Moreover, in thoracic aortic aneurysms, HOTAIR is closely associated with the expression of collagen types I and III in the extracellular matrix." (PMID 35845040, 2022).
thrombosis (1 paper, 2024). "Dysregulation of HOTAIR could aggravate the inflammatory state seen in disorders like APS, where immunological activation leads to placental thrombosis and even pregnancy loss." (PMID 39769397, 2024). "On the lncRNA side, targeting molecules like HOTAIR, which regulates inflammatory responses in APS, could help reduce the immune activation that contributes to placental thrombosis." (PMID 39769397, 2024).
thyroid nodule (1 paper, 2021). A small circumscribed mass in the THYROID GLAND that can be of neoplastic growth or non-neoplastic abnormality. "Next, analysis of suspicious thyroid nodules versus the contra-lateral tissue revealed that expression of MALAT1, HOTAIR, PVT1, and NEAT1 was significantly higher in malignant lesion than in contra-lateral normal tissue (P < 0.05)." (PMID 33030666, 2021). "The expressions of MALAT1, HOTAIR, PVT1 and the cytological class of a cohort of n = 34 thyroid nodules have been used to fit kernel distributions with Epanechnikov bases functions and positive support to determine the likelihoods p(MALAT1|tum)." (PMID 33030666, 2021). "Hence, each thyroid nodule has been classified as malignant if the probability p(mal.|MALAT1,HOTAIR,PVT1,cyt)." (PMID 33030666, 2021).
valvular heart disease (1 paper, 2020). "Because of the small size sample that only included valvular heart disease patients with SR or chronic AF, the regulatory effect of HOTAIR on Cx43 could not be evaluated in different types of heart disease." (PMID 33294032, 2020).
vocal cord polyps (1 paper, 2017). "The serum levels of HOTAIR and miR-21 exosomes were higher in 52 LSCC patients than in 49 patients with vocal cord polyps, and high expression levels of miR-21 and HOTAIR in LSCC patients are significantly associated with advanced clinical stages and LNM." (PMID 27802187, 2017).